FGL1 (fibrinogen like 1)
Description:
Immune suppressive molecule that inhibits antigen-specific T-cell activation by acting as a ligand of LAG3. LAG3-binding initiates a signaling that inhibits the T-cell receptor (TCR) in the immunological synapse, preventing T-cell activation. Binds LAG3 independently from MHC class II (MHC-II). Secreted by, and promotes growth of, hepatocytes.
Synonyms: HPS; HFREP-1; LFIRE-1; HFREP1; HP-041; LFIRE1
Tractability: Antibody: UniProt places it where antibodies can reach, with high confidence; its Gene Ontology location is reachable by antibodies, with high confidence; UniProt predicts a signal peptide or a membrane-spanning region. PROTAC: its protein half-life has been measured.
Gene: Protein-coding gene on chromosome 8 (17,863,528 to 17,910,378, reverse strand). Ensembl gene ENSG00000104760.
Subcellular location: Secreted
Gene Ontology:
Molecular function: protein binding; receptor ligand activity
Biological process: hepatocyte proliferation; negative regulation of T cell activation; negative regulation of T cell receptor signaling pathway; regulation of immune response; blood coagulation; signal transduction
Cellular component: extracellular region; plasma membrane; extracellular matrix; fibrinogen complex; non-collagenous component of interstitial matrix
Genetic constraint (gnomAD): Loss-of-function variants: 47 observed, 34.01 expected, observed/expected ratio (o/e) 1.38, 90% interval 1.09 to 1.75. The synonymous counts are far from expectation, so gnomAD's model fits this gene poorly and the ratio says little. Missense variants: 511 observed, 328.21 expected, observed/expected ratio (o/e) 1.56, 90% interval 1.45 to 1.67. Synonymous variants: 166 observed, 114.83 expected, observed/expected ratio (o/e) 1.45, 90% interval 1.27 to 1.64.
Homologues: Orthologues: chimpanzee FGL1 (98% identical), macaque FGL1 (96% identical), dog FGL1 (88% identical), pig FGL1 (88% identical), rabbit FGL1 (83% identical), mouse Fgl1 (82% identical), rat Fgl1 (80% identical), tropical clawed frog fgl1a (64% identical), guinea pig FGL1 (58% identical). Paralogues in human: FIBCD1 (38% identical), ANGPT2 (36% identical), FGL2 (36% identical), TNR (35% identical), ANGPT1 (35% identical), TNXB (35% identical), FGG (34% identical), ANGPTL2 (34% identical), FGB (34% identical), TNN (34% identical), ANGPT4 (34% identical), ANGPTL7 (34% identical), and 13 more.
Diseases named in the same sentence as FGL1 in open-access papers:
FGL1 is named in the same sentence as 92 diseases in open-access papers, as found by Europe PMC text mining. Sharing a sentence is not in itself a finding about the gene and the disease. The quoted sentences say what the papers report.
hepatocellular carcinoma (31 papers, 2019 to 2025). A malignant tumor that arises from hepatocytes. "Using a mouse subcutaneous tumor model of hepatoma cells, Hepa1-6, it was found that Fgl1 deficiency inhibited tumor growth." (PMID 38973608, 2024). "Fibrinogen-like protein 1 (FGL1) has been associated with improved survival in hepatocellular carcinoma (HCC)." (PMID 37115694, 2023). "While FGL1 is strongly implicated in the development and prognosis of a variety of diseases, its role in hepatocellular carcinoma (HCC) is still disputed." (PMID 35776395, 2022). "In hepatocellular carcinoma, FGL1 demonstrates dual roles, suppressing tumor cell proliferation while promoting immune evasion." (PMID 40978140, 2025). "Wild‐type and mice with specific ablation of Fgl1 in hepatocyte exhibit a comparable phenotype during experimental steatosis, hepatocellular carcinoma, and acute liver injury." (PMID 40832769, 2025). "Carvacrol (15 mg/kg) combined with sorafenib modulated HIF‐1α/STAT3/FGL1 pathway in a hepatocellular carcinoma (HCC) murine model." (PMID 40964147, 2025). "Arginase 1 and FGL-1 levels were extremely elevated in hepatocellular carcinoma, as they are in healthy liver tissues." (PMID 40788962, 2025). "In this issue of the JCI, Lin and colleagues evaluated the role of FGL1 in hepatocellular carcinoma (HCC)." (PMID 37115694, 2023). "Studies have shown that FGL1 is underexpressed in hepatocellular carcinoma (HCC) at both the protein and mRNA levels." (PMID 34975333, 2022). "Paradoxically, FGL1 also shows a suppressive effect on the growth of hepatocellular carcinoma cells." (PMID 34069373, 2021). "FGL1, also named as hepatocyte-derived fibrinogen-like protein-1 (HFREP1) 11, comprises a hepatocyte-secreted protein that was originally cloned in human hepatocellular carcinoma (HCC) 12-14 and conduces to mitogenic and metabolic activity." (PMID 33867830, 2021). "Recent research suggested that FGL1 is upregulated in gastric cancer tissues, while some studies revealed that it is downregulated and possibly acts as a tumor suppressor in hepatocellular carcinoma." (PMID 34956878, 2021). "Paradoxically, FGL1 has also shown a suppressive effect on the growth of hepatocellular carcinoma cells." (PMID 31489941, 2019). "The enhancement of FGL1 levels was regulated by IL-6 and it participates in the development of non-alcoholic fatty liver disease, hepatocellular carcinomas, and hepatocyte mitogenic activity." (PMID 30406363, 2019). "Moreover, Fgl1−/− mice developed a more severe hepatocellular carcinoma induced by diethynitrosamine (DEN)." (PMID 40832769, 2025). "Furthermore, previous studies indicated that IL6 can activate Stat3 to modulate the promoter activity of FGL1 in hepatocellular carcinoma (HCC)." (PMID 39085849, 2024). "Similarly, loss of FGL1 induced EMT in lung cancer, and expression of FGL1 in circulating tumor cells (CTCs) indicated poor prognosis in hepatocellular carcinoma (HCC)." (PMID 38539487, 2024). "FGL1 exhibits a dual role in hepatocellular carcinoma (HCC)." (PMID 38816776, 2024). "Here, we report that fibrinogen-like protein 1 (FGL1), a newly identified immune checkpoint ligand, was modified by acetylation at Lys 98 in hepatocellular carcinoma (HCC), which targeted it for proteasomal degradation." (PMID 37115693, 2023). "The results are similar in hepatocellular carcinoma (HCC), as cancer cells grow faster in FGL1-null mice, which is related to the activation of Akt and mTOR signal pathways." (PMID 36358792, 2022). "FGL1, also known as HFREP1 or hepassocin, was initially identified as an enriched transcript in hepatocellular carcinoma and rodent liver regeneration." (PMID 34957095, 2021). "Fibrinogen-like protein 1 (FGL1), an emerging hepatic factor in the fibrinogen super-family, is mainly expressed in the liver under steady-state conditions and is abundantly expressed in hepatocellular carcinoma." (PMID 36993960, 2023).
hepatocellular carcinoma (continued). "However, the FGL1 expression in circulating tumor cells (CTCs) and its clinical significance in hepatocellular carcinoma (HCC) remain unclear." (PMID 35273912, 2022). "Moreover, FGL1 is downregulated in hepatocellular carcinoma (HCC) in TCGA datasets." (PMID 34526102, 2021). "Thus, the deletion of Fgl1 in hepatocytes does not influence the installation and progression of hepatocellular carcinoma." (PMID 40832769, 2025). "Fibrinogen-like 1 (FGL1), also known as hepassocin or hepatocyte-derived fibrinogen-related protein 1 (HFREP1), is a protein produced by hepatocytes and was first identified as being highly expressed in human hepatocellular carcinoma (HCC)." (PMID 39329744, 2024). "However, the prognostic significance of FGL1-LAG-3 pathway and the correlation with PD-L1 in hepatocellular carcinoma (HCC) remain unknown." (PMID 32762721, 2020). "High FGL1 expression is associated with gefitinib resistance in non-small cell lung cancer (NSCLC), whereas low FGL1 expression is associated with sorafenib resistance in hepatocellular carcinoma (HCC), suggesting that FGL1 also plays significant roles in tumor therapy resistance." (PMID 37872170, 2023).
lung cancer (19 papers, 2013 to 2025). A malignant neoplasm involving the lung. "High FGL1 expression is associated with low responsiveness to anti–PD-1 therapy in lung cancer, and these results present a unique opportunity to validate similar combination regimens in HCC." (PMID 37115694, 2023). "A recent study showed that FGL1 promotes the progression of gastric cancer by facilitating the EMT process, whereas another study had suggested that loss of FGL1 could induce EMT in lung cancer." (PMID 34956878, 2021). "In addition, the study also found that lung cancer patients with high levels of FGL1 in plasma have relatively poor therapeutic effects of PD-1 inhibitors, suggesting an underlying association between the FGL1/LAG-3 and PD-1/PD-L1 immunotherapy resistance." (PMID 35273912, 2022). "In A549 lung adenocarcinoma cells with LKB1 overexpression, FGL1 knockdown significantly increases growth rate, migration of lung cancer cells, angiogenesis, and EMT, potentially mediating lung cancer metastasis." (PMID 41024301, 2025). "FGL1 is confined to the liver and pancreas under normal conditions, and elevated in human cancers such as lung cancer, prostate cancer, melanoma, and colorectal cancer, associated with a poor prognosis and resistance to anti‐PD‐1/B7‐H1 therapy." (PMID 39778025, 2025). "FGL1 has also been described as a mediator of immune evasion in certain cancers such as non‐small cell lung cancer or metastatic melanoma." (PMID 40832769, 2025). "Targeting both PD-L1 and FGL1 can enhance the immune response and anti-cancer effects in lung cancer, making FGL1 a promising biomarker for predicting the efficacy of PD-1/PD-L1 therapy as a novel immunotherapy target." (PMID 39085849, 2024). "FGL1 is also produced by other human cancer cells, including lung cancer, prostate cancer, melanoma, CRC, breast cancer, brain tumor, gastric cancer, and clear cell renal cell carcinoma." (PMID 38973608, 2024). "Upregulated FGL1 in tumor tissues correlated with poor prognosis in patients with non–small cell lung cancer, metastatic melanoma, gastric cancer, or renal cell carcinoma (RCC)." (PMID 38973608, 2024). "FGL-1 is increased in cross types of cancers, including lung cancer, pancreatic cancer, colorectal cancer and melanoma, and a higher level in tumors indicates poor prognosis." (PMID 36556955, 2022). "Cocultures were performed to explore the effect of FGL1 knockdown in lung cancer cells on T cells, concerning cytokine secretion and viability." (PMID 36268014, 2022). "FGA, FGB, FGG and FGL1 were downregulated during EMT of lung cancer and were mapped to the GO term ‘Fibrinogen complex’." (PMID 24093963, 2013). "We also verified that FGL1 is highly expressed in CCNE1(+) cells in these nine lung cancer samples using a public database, which could further support our findings." (PMID 41024301, 2025). "FGL1 may promote tumor growth, invasion, and migration; however, its role in lung cancer requires further investigation." (PMID 41024301, 2025). "FGL1 expression is upregulated in human solid tumors, including melanoma, lung cancer, prostate cancer, and colorectal cancer, with the highest percentage upregulation (35%) in lung cancer." (PMID 38556085, 2024). "FGL1 was found to be most expressed in epithelial cells of breast and colorectal cancer, followed by fibroblasts, and there was a significant difference in lung cancer." (PMID 39120585, 2024). "However, the role of FGL1 in cancer is likely contextual and lineage dependent, since its inhibition promotes growth in lung cancer cells but exerts antitumoral effects in gastric and colon cancer." (PMID 37115694, 2023). "Furthermore, the expression of FGL1 only indicates a poor prognosis in lung cancer and gastric cancer, but its prognostic significance in other tumors is unclear and needs clarification." (PMID 35111155, 2021).
lung cancer (continued). "Again, many of the immune-modulatory genes differentially expressed in the mouse model were site-specifically recapitulated, e.g., higher CCL2, CXCL5, CXCL9, CXCL11, CXCL14, CXCL17, and IDO1 in lung cancers and higher CXCL12, FGL1, and LAG3 in liver cancers." (PMID 33985562, 2021). "Moreover, multiple studies have shown that fibrinogen-like protein 1 (FGL1), another newly discovered ligand of LAG3 independent of MHC-II52, is upregulated in lung cancer, prostate cancer, melanoma, colorectal cancer, and breast cancer." (PMID 37817484, 2023).
gastric cancer (15 papers, 2021 to 2025). A primary or metastatic malignant neoplasm involving the stomach. "In FGL1+ gastric cancer, where a higher expression of FGL1 is positively associated with gastric cancer stage and lymph node metastasis, as well as the poor OS." (PMID 35111155, 2021). "This further proves that the silencing of FGL1 suppresses the proliferation of SGC-7901 gastric cancer cells." (PMID 36358792, 2022). "FGL1 was reported to be up-regulated in gastric cancer (GC) tissues and the survival time of GC patients with high FGL1 levels was markedly shorter than the patients with low FGL1 levels." (PMID 34975333, 2022). "Analysis of gastric cancer (GC) data collected from ATGC illustrated that contrast to normal gastric tissue, FGL1 expression is upregulated in GC, and was associated with poor prognosis." (PMID 33867830, 2021). "It has been discovered that overexpression of FGL1 in gastric cancer is correlated with tumor progression and poor prognosis." (PMID 34956878, 2021). "In contrast, overall survival time was found to be remarkably shorter in patients with gastric cancer with high FGL1 expression than in gastric cancer patients showing low FGL1 expression." (PMID 34069373, 2021). "Conversely, FGL1 may act as a tumor suppressor gene in lung adenocarcinoma with LKB1 mutation, the SGC-7901 gastric cancer cell line, and liver cancer." (PMID 41024301, 2025). "Knockdown of FGL1 could significantly increase the E-cadherin level of tumor cells and reduce the expression levels of vimentin and N-cadherin in tumor tissues, suggesting that FGL1 could promote the EMT process of gastric cancer." (PMID 35273912, 2022). "Similarly, in SGC-7901 gastric cancer cells, the downregulation of FGL1 is correlated with a decrease in vimentin and N-cadherin and an increase in E-cadherin." (PMID 36358792, 2022). "However, another opposite conclusion was also reached: E-cadherin was upregulated and the expression of N-cadherin and vimentin was suppressed when FGL1 was knocked out in SGC-7901 gastric cancer cells." (PMID 34526102, 2021). "In addition, in vitro tests have shown that FGL1 promotes the invasion and metastasis of gastric cancer cells." (PMID 34247148, 2021). "On the other hand, FGL1 expression has been examined in gastric cancer (GC) tissue, where FGL1 promotes GC proliferation, and patient overall survival time with increased FGL1 expression was significantly shorter." (PMID 36011329, 2022). "Previous preclinical studies have confirmed the correlation between FGL1 and the tumor EMT process in lung and gastric cancers." (PMID 34526102, 2021).
breast carcinoma (14 papers, 2019 to 2026). "Breast cancer is a well-known leading cause of death from malignant tumors in women, and FGL1 is remarkably upregulated in several types of tumors, including breast cancer." (PMID 33632231, 2021). "FGL1 has been identified as the next immune checkpoint target and dual-targeting FGL1/PD-L1 exhibited high synergistic therapeutic efficacy against breast cancer, even against TNBC." (PMID 35950033, 2022). "The regulatory effect of FGL1 on the TME was further demonstrated in a breast cancer model constructed using biomimetic nanomaterials designed to deliver a short interfering RNA targeting FGL1." (PMID 34526102, 2021). "In the present study, a breast cancer model was used to evaluate the synergistic immunotherapy efficacy of short interfering RNA (siRNA) targeting FGL1 (siFGL1) and Met." (PMID 33632231, 2021). "Our results indicate the potential of hybrid biomimetic membrane-camouflaged nanoparticles and combined Met-FGL1 blockade in breast cancer immunotherapy." (PMID 33632231, 2021). "A meta-analysis of Oncomine datasets showed that FGL1 expression was upregulated in lung, prostate, melanoma, colorectal, breast cancer and brain tumors but downregulated in pancreatic, breast, liver and head and neck cancers." (PMID 34526102, 2021). "We found that a combination of PD-L1/programmed death 1 signaling blockade and FGL1 gene silencing exhibited high synergistic therapeutic efficacy against breast cancer in vitro and in vivo." (PMID 33632231, 2021). "In addition, the combination of PD-1/PD-L1 signaling blockade and FGL1 gene silencing showed a high synergistic effect in the treatment of breast cancer." (PMID 34975333, 2022). "Moreover, the upregulation of FGL1 is related to a poor prognosis after treatment in several cancers, including breast cancer." (PMID 33632231, 2021). "While FGL-1 is upregulated in solid tumor tissues such as lung, prostate, and breast cancer, it remains unknown whether hematological malignancies also produce abundant FGL-1." (PMID 32787882, 2020). "We set up an experimental system using the MCF-7 breast cancer cell line, and amplified LAG-3 and FGL1 after bisulfite conversion of the extracted DNA, using methylation-specific PCR." (PMID 39796650, 2024). "FGL1, a Ligand of lymphocyte-activation gene 3 (LAG3), also known as hepassocin, HRFREP-1, and FREP1, is primarily expressed on the surface and within the cytoplasm of lung and breast cancer cells." (PMID 41024301, 2025). "We have also explored the GDC TCGA Breast Cancer (BRCA) dataset on the UCSC Xena browser, and our preliminary findings show that LAG-3 is indeed hypermethylated in its promoter region in contrast to the FGL1 promoter." (PMID 39796650, 2024). "FGL1 is found in the cytoplasm in NSCLC cells and on the surface of breast cancer cells." (PMID 35111155, 2021). "FGL1 is overexpressed in breast cancer in comparison to matched normal control (P = 0.0039), but there is no statistical difference between basal-like and non-basal-like group of breast cancer." (PMID 34717291, 2021).